RNA5SP524 (RNA, 5S ribosomal pseudogene 524)
Gene: Ribosomal RNA gene on chromosome X (148,008,100 to 148,008,215, reverse strand). Ensembl gene ENSG00000201285.
Homologues: Orthologues: chimpanzee 5S_rRNA (99% identical), guinea pig 5S_rRNA (60% identical). Paralogues in human: RNA5S1 (80% identical), RNA5S10 (80% identical), RNA5S11 (80% identical), RNA5S12 (80% identical), RNA5S13 (80% identical), RNA5S14 (80% identical), RNA5S15 (80% identical), RNA5S16 (80% identical), RNA5S17 (80% identical), RNA5S2 (80% identical), RNA5S3 (80% identical), RNA5S4 (80% identical), and 26 more.